RASSF9 (Ras association domain family member 9)
Description:
May play a role in regulating vesicuar trafficking in cells.
Synonyms: P-CIP1; PAMCI; PCIP1
Tractability: PROTAC: ubiquitination databases record sites on it.
Gene: Protein-coding gene on chromosome 12 (85,800,703 to 85,836,409, reverse strand). Ensembl gene ENSG00000198774.
Subcellular location: Endosome
Gene Ontology:
Molecular function: protein binding
Biological process: endosomal transport; protein targeting; signal transduction
Cellular component: cytosol; endosome; extracellular exosome; trans-Golgi network transport vesicle membrane; recycling endosome
Genetic constraint (gnomAD): Loss-of-function variants: 28 observed, 34.72 expected, observed/expected ratio (o/e) 0.81, 90% interval 0.6 to 1.11. The upper end of that interval is the gene's LOEUF score, 1.11, which puts it in group 4 of 6, group 1 being the genes least tolerant of losing a copy. Missense variants: 480 observed, 527.41 expected, observed/expected ratio (o/e) 0.91, 90% interval 0.84 to 0.98. Synonymous variants: 183 observed, 187.95 expected, observed/expected ratio (o/e) 0.97, 90% interval 0.86 to 1.1.
Homologues: Orthologues: chimpanzee RASSF9 (99% identical), macaque RASSF9 (97% identical), dog RASSF9 (91% identical), pig RASSF9 (90% identical), rabbit RASSF9 (90% identical), guinea pig RASSF9 (87% identical), mouse Rassf9 (85% identical), rat Rassf9 (85% identical), tropical clawed frog rassf9 (45% identical), zebrafish rassf9 (39% identical), Drosophila melanogaster meru (17% identical). Paralogues in human: RASSF10 (37% identical), RASSF8 (17% identical), RASSF7 (13% identical).
Diseases named in the same sentence as RASSF9 in open-access papers:
RASSF9 is named in the same sentence as 14 diseases in open-access papers, as found by Europe PMC text mining. Sharing a sentence is not in itself a finding about the gene and the disease. The quoted sentences say what the papers report.
gastric cancer (6 papers, 2019 to 2025). A primary or metastatic malignant neoplasm involving the stomach. "For example, miR-1269 in gastric cancer (GC) acts on Ras association domain family member 9 (RASSF9) to regulate AKT-mediated pathways to promote the proliferation and migration of cancer cells, enter the GI-S cycle, and inhibit cell apoptosis." (PMID 40001986, 2025). "In contrast, two recent studies have described that RASSF9 is decreased in breast and gastric cancer, and that RASSF9 suppresses the proliferation of these cancer cells." (PMID 34341331, 2021). "MicR-1269 overexpression targets RASSF9 to regulate AKT, thereby promoting gastric cancer progression." (PMID 35609320, 2022).
alopecia (1 paper, 2011). Hair loss usually from the scalp. "The RASSF9-null mice exhibited interesting phenotypes that resembled human ageing, including growth retardation, short lifespan, less subcutaneous adipose layer and alopecia." (PMID 21445300, 2011).
breast carcinoma (1 paper, 2019). "Recently, it was reported that RASSF9 suppresses cell proliferation in breast cancer." (PMID 31768130, 2019). "Evidence suggests that RASSF9 inhibits breast cancer cell growth." (PMID 31768130, 2019).
esophageal tumor (1 paper, 2021). "Taken together, the data reveal that TAK1‐mediated phosphorylation of RASSF9 at Ser284 negatively regulates esophageal tumor cell proliferation via inhibition of the RAS/MEK/ERK axis." (PMID 33717835, 2021). "Our study showed that RASSF9, a member of N‐RASSFs, is a target of TAK1 and transduces its inhibitory effect on esophageal tumor cell growth." (PMID 33717835, 2021). "Our results suggest that unlike C‐RASSFs, RASSF9 is an activator of esophageal tumor cell growth." (PMID 33717835, 2021).
glioma (1 paper, 2021). A benign or malignant brain and spinal cord tumor that arises from glial cells (astrocytes, oligodendrocytes, ependymal cells). "In glioma grade III, highly activated DEGs included CFAP45, PLBD1, RASSF9, IGKV3-11, IGKV1-5, and NTS, while highly downregulated DEGs included NPAS4 and LINC01007." (PMID 33948562, 2021).
liver fibrosis (1 paper, 2023). "The established markers of LyECs (Prox1, Pdpn, Ccl21a, Mmrn1, Reln, and Rassf9) are highly expressed in hepatic LyECs from CCl4-induced liver fibrosis, NASH and BDL mice." (PMID 36632228, 2023).
non-small cell lung carcinoma (1 paper, 2021). A group of at least three distinct histological types of lung cancer, including non-small cell squamous cell carcinoma, adenocarcinoma, and large cell carcinoma. "In addition, we also measured RASSF9 expression in several non-small cell lung cancer cell lines, including A549, H1299, and H1650." (PMID 34341331, 2021).
ovarian carcinoma (1 paper, 2022). A malignant neoplasm originating from the surface ovarian epithelium. "While the expression of NOG, S1PR1, BTG4, and CREB5 genes was significantly increased, that of RASSF9, DNMT1, BST2, and SETD1A genes was significantly decreased in CFP1-deleted A2780 and ES-2 ovarian cancer cells, based on qRT-PCR results." (PMID 35864225, 2022).
tumor (8 papers, 2015 to 2025). "The expression of NOG and S1PR1 genes was also increased in CFP1-deleted tumor tissue cells, while the expression of RASSF9 and BST2 was decreased significantly." (PMID 35864225, 2022). "Pharmacological interventions revealed that activation of the MEK/ERK axis is responsible for RASSF9-induced tumor cell proliferation." (PMID 34341331, 2021). "Subcutaneous tumorigenesis study further confirmed that TAK1 lost the inhibitory effect on RASSF9 S284A induced tumor cell growth." (PMID 33717835, 2021). "Increased expression of RASSF9 augmented tumor cell proliferation, whereas knockdown of RASSF9 resulted in the opposite outcome." (PMID 33717835, 2021). "Meanwhile, the upregulation of RASSF9 expression enhanced the proliferation of tumor cells, while downregulation of RASSF9 resulted in the opposite outcome." (PMID 34341331, 2021). "TAK1 is decreased in esophageal squamous tumor cells, RASSF9 binds to RAS and causes RAS dimerization, which triggers RAF/MEK/ERK signal transduction and tumor cell proliferation." (PMID 33717835, 2021). "Increased expression of RASSF9 promotes NSCLC cell proliferation, whereas knockdown of RASSF9 suppresses tumor cell proliferation." (PMID 34341331, 2021). "Collectively, our data indicate that RASSF9 plays a key role in tumorigenesis of NSCLC by stimulating tumor cell proliferation, which relies on activation of the MEK/ERK axis." (PMID 34341331, 2021). "Our results revealed that elevated expression of RASSF9 induced by LV-RASSF9 greatly stimulated cell growth, as evidenced by increased tumor mass, volume, and weight." (PMID 34341331, 2021). "For instance, in BM178, a number of significantly downregulated genes were observed on the chromosome arm rearranged by chromothripsis, including two tumor suppressors (the RASSF3 and RASSF9 members of the RAS-associated family of tumor suppressors; Fig5A)." (PMID 26415501, 2015). "RASSF9 plays a role in regulating tumor proliferation and maintaining epidermal homeostasis." (PMID 36140679, 2022). "Moreover, the hematoxylin/eosin (H&E) staining showed that tumor cells in the RASSF9 group were presented in nest-like distribution, and the nuclei were deeply stained, suggesting these cells grew vigorously." (PMID 34341331, 2021). "Moreover, the effects of RASSF9 on NSCLC cell proliferation were further confirmed in vivo by using a subcutaneous tumor model." (PMID 34341331, 2021). "We next sought to determine whether TAK1 regulates tumor cell proliferation through RASSF9." (PMID 33717835, 2021). "RASSF9 promotes the proliferation of NSCLC cells, while knockdown of RASSF9 inhibits the growth of tumor cells." (PMID 34341331, 2021). "Following phosphorylation of RASSF9 by TAK1, RAS dimerization is disrupted, leading to a blockade of RAF/MEK/ERK signal transduction and retardation of tumor cell growth." (PMID 33717835, 2021). "RASSF9 has been shown to positively regulate RAS signaling by inducing RAS dimerization, which activates downstream signal pathway including MEK and ERK to drive tumor cell proliferation." (PMID 34341331, 2021). "Since miR-1269 regulated cell proliferation and apoptosis in human GC cells and RASSF9 was validated as a direct target of miR-1269; in the next experiments, RASSF9 was knocked down in AGS/MKN-45 cells by RNA interference to validate its involvement in the pro-tumor functions of miR-1269." (PMID 31768130, 2019).
cancer (5 papers, 2021 to 2025). A tumor composed of atypical neoplastic, often pleomorphic cells that invade other tissues. "There is growing evidence that the dysregulation of RASSF9 expression is closely associated with many human diseases, including cancer." (PMID 34341331, 2021). "Methylation of RASSF1, RASSF2, RASSF3, RASSF6, RASSF7, and RASSF9, from the RASSF regulator family was strongly associated with expression of several GMDs in a variety of cancer categories." (PMID 33676569, 2021). "However, the exact roles of RASSF9 in tumorigenesis in a variety of cancers, especially in NSCLC, are not fully understood." (PMID 34341331, 2021). "miR-1269a can regulate the occurrence and development of cancer by targeting downstream genes (CXCL9, SOX6, FOXO1, ATRX, RASSF9, SMAD7, HOXD10, and VASH1)." (PMID 35252180, 2022).
infection (2 papers, 2011 to 2019). The state of being infected such as from the introduction of a foreign agent such as serum, vaccine, antigenic substance or organism. "Conversely, re-expression of RASSF9 by infection with the Adv/HA-RASSF9 recombinant virus inhibited the BrdU incorporation in RASSF9−/− keratinocytes (P<0.05)." (PMID 21445300, 2011). "Additionally, in RASSF9−/− keratinocytes there was a drastic down-modulation of terminal differentiation markers, which could be rescued by infection with a recombinant adenovirus, Adv/HA-RASSF9." (PMID 21445300, 2011). "In addition, we validated several additional genes (SLC22A8, RASSF9, and NEAT1) which were highly upregulated in Huh7.5.1 cells, yet not within this infection responsive cluster, as controls." (PMID 30700707, 2019).
RASSF9 also shares sentences with these, for which no sentence is quoted: colorectal cancer (1 paper); hepatocellular carcinoma (1); lung carcinoma (1).